CD4 (CD4 molecule)
Diseases named in the same sentence as CD4 in open-access papers (continued):
Sharing a sentence is not in itself a finding about the gene and the disease.
cancer (continued). "These modified nanocarriers can be made to target certain immune cells, such as CD4+ T-cells, or elements of the cancer microenvironment, increasing the therapeutic index of checkpoint inhibitors, cytokines, and immunomodulators." (PMID 40860882, 2025). "In contrast, cancer zone B exhibited elevated scores for M1 and M2 macrophages, CD4+ T cells, CD8+ T cells, and B cells, indicating more extensive immune infiltration." (PMID 40723284, 2025). "Functional assays, including wound healing and cell migration assays, were conducted across various cell types, including CD4+ T cells and cancer cells, to evaluate the impact of GPR15LG on CXCL12-mediated CXCR4 signaling." (PMID 40394646, 2025). "In contrast, we observed negative correlations between UCK2 expression and resting memory CD4+ T cells, monocytes, M2 macrophages, resting mast cells in various cancers." (PMID 39931080, 2025). "CCR5+CD4+ T cells exhibit increased cellular immunogenicity and play a role in infectious diseases, host defense, and cancer progression." (PMID 40205945, 2025). "This study identified increased age, reduced absolute counts of CD4+CD28− T cells, and elevated absolute counts of CD4+CD38− T cells as independent risk factors for CRF in pan-cancer patients, as determined by multivariate logistic regression analysis." (PMID 41018226, 2025). "CD4+ T cells are antitumor effectors via coordinating innate and antigen-specific immune responses and killing cancer cells." (PMID 40107245, 2025). "The novel PIs will be further refined in silico and their biological efficacy tested via assays carried out on cancer cell lines and CD4+/CD8+ T cells." (PMID 40245195, 2025). "The MHC+fibroblasts, known as antigen-presenting cancer-associated fibroblasts (apCAFs), present cancer-specific MHC II peptides to nearby CD4+T cells." (PMID 39897591, 2025). "Evidence suggests that CD8+ and NK cells of the immune system, which play an important role in the defense against cancer cells and are activated during exercise, are specifically and significantly activated at high intensity (more so than CD4 + cells)." (PMID 40694552, 2025). "T cell depletion studies revealed that CD8+ T cells function as the major killer cells, while CD4+ T cells also play a role in killing cancer cells." (PMID 39498880, 2025). "HLAIIPred has shown potential applications to peptide-based cancer vaccine design, particularly to the recognition of neoantigen by CD4+ T cells." (PMID 40739437, 2025). "The proposed model incorporating short diameter, lymphocyte ratio, CD3+ T cell count, and CD4+ T cell ratio demonstrates significant potential in differentiating benign from malignant lymphadenopathy in HIV patients." (PMID 40989183, 2025). "Novel drug delivery systems provide a versatile platform for precise CD4+ T-cell modulation in cancer therapy, enhancing antitumor responses while reducing toxicity." (PMID 40860882, 2025). "In pan-cancer, TRPM6 showed a robust positive association with resting memory CD4+ T cells (P < 0.01)." (PMID 41562086, 2025). "Given the relative enrichment of class II HLA genes with autoimmune phenotypes, future studies exploring the relationship between TCR repertoire and genotype of CD4+ T cells in patients with cancer will be of high importance." (PMID 40712021, 2025). "CD4+ Th1 cells have also been found to endow cDC1 with cancer-impeding functions and to prevent CD8+ T cell exhaustion in the TME." (PMID 41194931, 2025). "This aligns with studies in other cancer types showing that CD4+ CTLs have a positive predictive outcome." (PMID 40897819, 2025). "Specifically, an increase in CD4+ TNF receptor superfamily Member 9 (TNFRF9+) regulatory T cells was observed in cancers such as iCCA, ccRCC, and BCC following ICB therapy." (PMID 40054456, 2025). "Immunofluorescence staining of cancer tissues showed reduced CD4+/CD25+ T cell infiltration and significantly increased CD3+/CD8+ T cell infiltration in the G&P group compared to the other groups." (PMID 41488675, 2025).
cancer (continued). "The PIs will be further refined in silico and tested via assays carried out on cancer cell lines and CD4+/CD8+ T cells." (PMID 40245195, 2025). "At the same time, this pan-cancer study also found that the expression of PCLAF is positively correlated with activated CD4+ T cells and T helper 2 (Th2) cells." (PMID 40302936, 2025). "This interaction enhances the effector function of cancer-specific CD4+T cells and contributes to the tumor-suppressive effect of apCAFs." (PMID 39897591, 2025). "Nevertheless, it was observed that among T-cells, naive CD4+ T cells showed the highest number of dysregulated genes, indicating the high influence of cancer cells on naive CD4+ T cells." (PMID 40906153, 2025). "Nevertheless, these data collectively demonstrated robust induction of an effective CD8+ and CD4+ T cell immune response by cancer vaccine." (PMID 39888994, 2025). "DNBscore was positively associated with infiltration of cancer‐associated fibroblast (CAF), hematopoietic stem cell, and endothelial, while was negatively associated with immune cells, including CD4+Th1 cell, CD4+Th2 cell, CD8+ naïve T cell, and NK cell." (PMID 40788991, 2025). "By integrating our preceding analysis of immune infiltration, we further assessed the relationship between TRMT112 and the populations of CD8, CD4, and B cells from a comprehensive cancer perspective." (PMID 41235342, 2025). "In the tumor microenvironment, excessive methionine uptake by cancer cells reduces intracellular methionine levels in CD4+ T cells." (PMID 41278473, 2025). "Our research also demonstrated that FAM111B is negatively correlated with Th1 CD4+ T cells and positively correlated with Th2 CD4+ T cells across various cancers, indicating its role in shifting the balance of these cell populations." (PMID 40243892, 2025). "A dramatic expansion of CD4+CD8+ double positive (DP) T lymphocytes was observed on Day 3 post administration of 225Ac-anti-CCR8 in both cancer models (CT26: p=0.0234, MC38: p<0.0001)." (PMID 41035646, 2025). "This immunological mechanism is attributed to the immune responses mediated by NK cells and CD4+T cells, and data suggest that saponin adjuvants are effective adjuvants for cancer vaccines." (PMID 40333256, 2025). "Clinicians should prioritize early ART initiation and CD4 monitoring to optimize immune status before cancer treatment." (PMID 41573453, 2025). "In our investigation, we discerned a diverse array of T cell subtypes from the ten cancer types, comprising 12 distinct CD4+ and 15 CD8+ T cell subsets based on signature genes." (PMID 40054456, 2025). "Research-grade TENDU constructs (LUR1-6) were tested in patient blood in the ex vivo blood loop assay pre and post a TTD-containing vaccination to determine if CD8+ or CD4+ T cell recall responses can be induced against the cancer epitopes in TENDU." (PMID 40520577, 2025). "The results indicated that CD8+ T cells displayed the highest cytotoxicity, whereas CD4+ T cells showed very low cytotoxicity against MDA‐MB‐231 cancer cells in the in vitro T cell‐mediated cancer cell killing assay." (PMID 39932384, 2025). "Understanding how CD4+ T cells respond to cancer immunotherapies is crucial for optimizing treatment strategies and promoting durable antitumor immunity." (PMID 40634636, 2025). "(2022) also described a significant reduction in both PD1 expression in HIV-positive CD4+ T cells and PD-L1 expression in cancer cells by Silymarin." (PMID 40332448, 2025). "Taken together, these results suggest that CD4+ T28zT2 T cells eliminated cancer cells mainly through secreting Granzyme B and IFN-γ." (PMID 40107245, 2025). "The common markers of effector T cells, helper T cells, and regulatory T cells, which were CD8, CD4, and Foxp3, respectively, were stained on the cancer tissue sections of C57BL/6 mice." (PMID 39917292, 2025).
cancer (continued). "A quantitative assessment was performed using image analysis software on slides subjected to immunohistochemical staining for CD4, CD8, and PD-L1 because of their close association with the cancer immune cycle." (PMID 41463155, 2025). "Cytotoxic T cells (CD8) destroy cancer cells, and helper T cells (CD4+) provide support to the immune cells." (PMID 40837403, 2025). "HIV infection results in depletion of CD4+ T cells, predisposing PWH to opportunistic infections and AIDS-defining cancers." (PMID 40459946, 2025). "Investigation of predictors of CD4 count trajectories after cancer is the focus of another ongoing project in RESPOND." (PMID 41463249, 2025). "Together, these clinical studies in cancer patients strongly support RCOR2’s role in evading CD4+CD8+ T cell surveillance." (PMID 40608411, 2025). "Differences in the TME, even within the same cancer type, can shape how CD4+ T cells respond to immunotherapies." (PMID 40634636, 2025). "A considerable proportion of clonal 6p LOH is observed in patients with BRCA1/2 alterations, and the functional consequence of 6P LOH in HRD cancers, namely, an increase in dysfunctional CD4+ and CD8+ T cells, is also demonstrated." (PMID 40830526, 2025). "In cancer, the three signals initiate proliferation and differentiation of CD4+ into T helper 1 (Th1) cells while suppressing progression towards other lineages, while CD8+ T cells differentiate into cytotoxic T cells." (PMID 40560407, 2025). "Recent evidence suggests that the CD4+ T cell subset plays a protective role against cancer progression by augmenting the tumoricidal activity of other antitumor effector cell subsets." (PMID 40958865, 2025). "Our adaptive immune system relies substantially on the CD4+ T cell responses to eliminate invasive components of pathogens or cancer cells." (PMID 40739437, 2025). "On the other hand, Th17 and Th1 CD4+T-helper cells have been observed to trigger cytokine secretion, such as TNFα, and IL-17 which have anti-cancer activity." (PMID 40352931, 2025). "The selection criteria yielded seven cell types for TNBC: iCAF, myCAF, basal cancer cells, macrophages, monocytes, CD4+ and CD8+ T cells." (PMID 41188599, 2025). "In fact, we recently demonstrated that, similar to cancer cells, glutamine deprivation in CD4+ T cells also regulate glycolysis." (PMID 41235226, 2025). "In malignant tumors, significant interactions were detected between T cell subtypes (CD4+, CD8+, and NK cells)." (PMID 40190189, 2025). "Upon exposure to the AOM/DSS model, we observed that infiltrated T cells exhibit a gradually increased expression of branched N-glycans along CAC development, from inflammation to premalignancy and cancer, both on CD4+ and CD8+ T cells in WT mice." (PMID 40087977, 2025). "The immune infiltration reveals that CD4+ T cells generally show higher infiltration levels across the 14 cancer types." (PMID 40004489, 2025). "A study analyzing 21 human cancer types via scRNA-seq revealed that CD4+ T cells in tumors commonly undergo differentiation into IFNG+ Tfh/Th1 dual-functional cells and TNFRSF9+ Treg cells." (PMID 40634636, 2025). "CD4+ T cell induction for cancer immunoprevention and therapy has several distinct advantages compared with conventional immunotherapies directed at CD8+ T cells." (PMID 39744942, 2025). "PWH with CD4 + <200 cells/mm3 at cART initiation showed the highest cancer incidence, 5% after 5 years, versus 3% for CD4+ 200–349 and 2% for CD4+ >350 (p < .001)." (PMID 40437996, 2025). "CD4 T cells realize its antiproliferative effect through the advancement of the cancer cell cycle in G1/S." (PMID 40985028, 2025). "Despite these promising results, the full spectrum of immune responses elicited by cancer vaccines targeting CD4+ helper T cells remains to be extensively explored in the clinic, particularly considering the plasticity of CD4+ T cell subsets." (PMID 40543509, 2025).
cancer (continued). "Combining checkpoint inhibitors with strategies that promote CD4+ T-cell differentiation into effector subsets holds promise for improving the efficacy of cancer immunotherapies." (PMID 40860882, 2025). "Studies also show that a decreased CD4+ count is significantly linked to HCC, suggesting a possible direct role for immune suppression in cancer development." (PMID 41471957, 2025). "We demonstrate the importance of capturing the dynamic nature of CD4+ T cells in understanding CRC risk, and prioritize genes for further investigation in cancer prevention." (PMID 40974097, 2025). "Nanoformulation-based CD4+ T-cell therapies hold immense promise for cancer treatment by enhancing antitumor immune responses." (PMID 40860882, 2025). "According to data from Pan-cancer RNA-seq, immune cells such as resting CD4+T cells and activated mast cells were higher in ANO1-high group, while activated CD4+ Tcells and dendritic cells, plasma cells were higher in ANO1-low group." (PMID 40396170, 2025). "We then compared cell‐type specificity of naïve against memory CD4+ T cells for all 255 gene‐cancer pairs with robust MR and colocalization evidence in either naïve or memory CD4+ T cells." (PMID 41216857, 2025). "There were statistically significant differences in indicators such as age, yearly income, alcohol drinking, family history of cancer, high-risk HPV infection, vaginal CD4, CD8,CD4/CD8, and IL-10 levels between the control group and the CIN group." (PMID 41142594, 2025). "PHF6 was positively correlated with resting memory CD4+ T cells across many cancer types but negatively correlated with activated NK cells." (PMID 41515604, 2025). "Both cDC1 and cDC2 exhibit conserved functions in priming CD4+ T cells that in turn contribute to the activation of anti‐cancer CTL responses via the secretion of proinflammatory mediators." (PMID 40878038, 2025). "Nanoformulations provide an effective and well-regulated means of adjusting CD4+ T-cell responses in cancer immunotherapy." (PMID 40860882, 2025). "Lower lymphocyte counts, particularly in CD4 T cells and natural killer cells, have been correlated with increased levels of physical fatigue in cancer survivors." (PMID 40095296, 2025). "In a mouse CRC model, Sini Decoction can increase the expression of CD8+ T lymphocytes and decrease CD4+ T cells and inflammatory cytokine levels, effectively intervening in cancer progression." (PMID 40791867, 2025). "The induction of antitumor CD4+ T cells has gained considerable interest for cancer vaccine efficacy during the past decade." (PMID 40543509, 2025). "Rapidly proliferating cells, both cancer and active T cells expressing CD4 and CD8, were compromised by the CCRT treatment in our study." (PMID 40411616, 2025). "We explored the relationships between CD68 expression and six TIICs (B cells, CD4+ T cells, CD8+ T cells, macrophages, NK cells and Cancer associated fibroblast) focusing on COAD, ESCA, LIHC, PAAD and STAD." (PMID 40918116, 2025). "Our results indicated a positive correlation between UCK2 expression and activated memory CD4+ T cells, T follicular helper cells, M0 macrophages, M1 macrophages, and activated mast cells across several cancers." (PMID 39931080, 2025). "At the early stage of cancer metastasis, IL-22 produced by tissue-resident iNKT17 cells facilitates the extravasation of cancer cells into the liver, and CD4+TRM cell-derived IL-22 promotes tumor metastasis at the late stage." (PMID 39820040, 2025). "RV001-specific CD4+ T cells were shown to mediate cytotoxicity against a RhoC-expressing cancer cell line in an HLA-class II-dependent manner." (PMID 40333248, 2025). "B cells in germinal cancers participate in antitumor immunity through antigen presentation, which activates CD4+ TFH cells." (PMID 40166933, 2025).
cancer (continued). "In the lymphoid compartment, cancer PBMCs exhibit substantial reductions in B cells (immature, intermediate and memory) and CD4 T and CD8 T cells (including central and effector memory phenotypes)." (PMID 40340807, 2025). "Several studies have targeted peripheral CD4+T-cells in human cancers in peripheral blood or in tertiary lymphoid structures." (PMID 40226614, 2025). "HLA-DR, a class II MHC molecule, is involved in antigen presentation to CD4 + T cells, a crucial process for mounting an adaptive immune response against cancer." (PMID 40853959, 2025). "RBP4 was also negatively correlated with CD4+ Th2 T cell infiltration across 33 cancers, with statistically significant correlations being observed in 13 cancer types." (PMID 40004479, 2025). "This review aims to explore the immunological significance of CD4+ T-cells in cancer and their modulation using novel drug delivery systems." (PMID 40860882, 2025). "Tregs, a subset of CD4 + T cells, often play an immunosuppressive role within the TME across various types of cancer and their activity is associated with cancer progression and resistance to immunotherapies." (PMID 41035074, 2025). "HD-PTP recruits USP8 to deubiquitylate CTLA-4 in cancer cell lines, mouse CD4-positive T cells and cancer cell-derived exosomes." (PMID 41031910, 2025). "Results showed that PRKAG1 expression was positively correlated with the infiltration of CD4+ T cells, CD8+ T cells, B cells, and cancer-associated fibroblasts." (PMID 40958861, 2025). "Inhibition of CD4+ and CD8+ T cell response to HPV accelerates cervical cancer development, as HPV is a major risk factor in this cancer group." (PMID 40136652, 2025). "Despite this compelling evidence, few cancer vaccines are specifically designed to stimulate CD4+ Th1 cells." (PMID 40543509, 2025). "Compared with normal tissues, CD8+ T cell infiltration was significantly increased in most cancer types, while CD4+ T cell infiltration was significantly decreased in most cancers." (PMID 40004489, 2025). "The induction of an antitumor CD4+ T helper response is essential for the efficacy of therapeutic cancer vaccines." (PMID 40543509, 2025). "Maintaining high CD4 counts (≥500–750 cells/μL) through early ART initiation, sustained viral suppression, and regular monitoring is key to mitigating cancer risk." (PMID 41295583, 2025). "GSDMD expression exhibited a strong correlation with monocytes, resting mast cells, resting dendritic cells, and activated CD4 memory T cells in most cancers." (PMID 40491921, 2025). "Specifically, GPR15LG enhances CXCL12-mediated CXCR4 signaling synergistically, promoting wound healing and cell migration across various cell types, including CD4 + T cells and cancer cells." (PMID 40394646, 2025). "Studies in other cancers, such as colon cancer and melanoma, have also identified similar cytotoxic CD4+ T cell populations." (PMID 40177538, 2025). "Cluster 5 consisted of cancer-associated fibroblasts (CAFs), CD14+ monocytes, CXCL13+ CD4+ follicular helper cells, and GZMA+ CD4+ memory/effector T cells." (PMID 41279139, 2025). "To determine if EphB4 knockdown in the cancer cell directly affects the CD4 + T cell state, we cocultured control or EphB4 shRNA cancer cells with CD4 + T cells and conducted flow cytometry." (PMID 39489818, 2025). "The dualistic nature of Th17 responses underscores the complexity of CD4+ T-cell-mediated immune modulation in cancer." (PMID 40860882, 2025). "In tumors, we detected a higher abundance of proliferating CD8+CD39+ cancer-specific T lymphocytes and a decrease in the frequency of CD4+FoxP3+ Treg cells following infusion of GFP+Olfr644−/− and GFP+Vmn2r29−/− macrophages." (PMID 40588561, 2025). "SLC43A2, the primary methionine transporter on cancer cell membranes, mediates this metabolic competition; its deletion restores methionine metabolism in CD4+ T cells." (PMID 41278473, 2025).